CGAS (cyclic GMP-AMP synthase)
Diseases named in the same sentence as CGAS in open-access papers (continued):
Sharing a sentence is not in itself a finding about the gene and the disease.
Sepsis (continued). "In conclusion, the less severe sepsis that was observed in CLP and LPS models in cGAS-/- mice compared with WT mice was possibly due to a synergy between LPS and cfDNA that increased mitochondrial dysfunction and inflammatory responses." (PMID 34768881, 2021). "Similar results were also identified by analysis of transcriptomic data derived from the GSE66890 dataset, which showed that the level of cGAS and STING expression were increased in patients with sALI patients with sepsis." (PMID 34218252, 2021). "Discovery of the cGAS-STING signaling pathway opens up a new route for the study of the sepsis mechanism and further emphasizes the crucial role of mtDNA in sepsis." (PMID 31205588, 2019). "In this part, cGAS-STING regulates the immune responses to mtDNA, and its resulting effect in sepsis remains further investigated." (PMID 31205588, 2019). "Notably, inflammasome pathways such as the NLRP3 inflammasome, along with NF-κB, JAK-STAT, MAPK, and cGAS-STING pathways, play central roles in the intracellular signal transduction responsible for sepsis and SIC." (PMID 40649892, 2025). "Directly inhibit cGAS and STING to block the inflammatory pathways, preventing SASP in sepsis." (PMID 40153575, 2025). "During sepsis, cfDNA primarily triggers inflammatory responses by activating specific PRR pathways, including TLR9-myeloid differentiation primary response 88 (MyD88), AIM2 inflammasome, and cGAS-STING pathways." (PMID 41327452, 2025). "Notably, pharmacological inhibition of the cGAS-STING pathway attenuates Kupffer cell senescence, highlighting a potential therapeutic target for preventing immune aging in sepsis." (PMID 40221420, 2025). "In vivo, the absence of cGAS reduces sepsis-induced acute lung injury by promoting the macrophage transformation from M1 to M2 phenotype." (PMID 38613801, 2024). "Hence, understanding the endogenous mechanisms/molecules that regulate the cGAS-STING pathway and developing methods of restoring the imbalanced pro- and anti-inflammatory pathways is needed to induce recovery from sepsis." (PMID 37759732, 2023). "Thus, altered concentrations of PUFAs and their metabolites, and failure to suppress the cGAS-STING system at an appropriate time, leads to the onset of sepsis." (PMID 37759732, 2023). "Not too dissimilar, a study using RU.521 to inhibit the cGAS pathway demonstrated improved cardiac function in mice with sepsis, where treatment with RU.521 alleviated the inflammatory response and prevented further cardiac damage induced by oxidative stress." (PMID 37656236, 2023). "Hence, we produced sepsis models, using cecal ligation and puncture (CLP) and LPS injection, and examined in vitro cGAS-/- macrophages." (PMID 34768881, 2021). "Combining the identified top 20 differentially expressed proteins and KEGG pathway enrichment analysis, it was inferred that the cGAS-STING signaling pathway might play a potential role in CD4+ T lymphocyte PANoptosis, regulated by NUFIP1-mediated ribophagy in sepsis." (PMID 40995563, 2025). "It was found that sepsis induced marked ribosome collisions in CD4+ T lymphocytes, which aligned with previous studies indicating that ribosome dynamics could exert dual effects as both cGAS co-activators and autophagy inducers." (PMID 40995563, 2025). "Although we demonstrated that STING directly induces ferroptosis in a manner dependent on its interaction with NCOA4 but independent of cGAS or TBK1 in lethal sepsis, whether the role of STING upon iron metabolism orchestrates immune homeostasis still requires further investigation." (PMID 35902564, 2022). "In sepsis, Toll-like receptor (TLR) 9, absent in melanoma 2 (AIM2), and cyclic GMP-AMP synthase (cGAS) are the principal PRRs responsible for sensing cfDNA." (PMID 41327452, 2025). "MN-containing cells trigger inflammation by activating the cGAS-STING system, which can occur even in sepsis, and other inflammatory conditions, including, but not limited to, radiation-induced tissue damage." (PMID 37759732, 2023).
Sepsis (continued). "However, unlike STING−/−, cGAS depletion failed to prevent against sepsis-induced mortality and tissue injury, implying that other DNA sensors may play a more important role during sepsis." (PMID 33485379, 2021). "Interestingly, we discovered that STING-mediated macrophage ferroptosis in sepsis does not rely on the classical elements of the STING pathway, including cGAS, TBK1, and cytokines transcription from NF-κB." (PMID 35902564, 2022).
colitis (40 papers, 2020 to 2026). Inflammation of the colon. "cGAS-deficient mice were insensitive to dextran sulfate sodium (DSS)-induced colitis and suffered from lower disease severity." (PMID 40621423, 2025). "The UC-associated Otud3 SNP increases the susceptibility to colitis through cGAS-STING-mediated type I IFN responses due to enhanced K27-linked polyubiquitination of STING." (PMID 41155222, 2025). "Thereby, genetic ablation of cGAS in mice exacerbates chemically induced colitis and colitis-associated colorectal cancer (CAC)." (PMID 40470467, 2025). "When subjected to DSS, cGAS-deficient mice showed worsened colitis and were demonstrated to have downregulation of autophagy proteins, including Beclin-1 via Western blot analysis and immunofluorescence staining." (PMID 39050748, 2024). "Together, these results reveal the potential pathogenic role of the cGAS–STING signaling pathway in colitis." (PMID 38525112, 2024). "Our rescue experiments demonstrated that blocking the cGAS-STING pathway partially rescues the colitis phenotype in Dhx9-deficient mice, supporting the idea that cGAS-STING activation contributes to colitis pathogenesis." (PMID 38594251, 2024). "When subjected to DSS, cGAS-deficient mice exhibit worsened colitis as well as downregulation of autophagy proteins." (PMID 39050748, 2024). "and Escherichia coli compared with DSS-induced IBD model mice; furthermore, cGAS knockout mice are less susceptible to DSS-induced colitis, suggesting a relationship between the cGAS gene in altering intestinal ecology and IBD pathogenesis." (PMID 37389342, 2023). "Treatment with RU.521 can also reduce cGAMP levels and decrease STING, TBK1, and IRF3 phosphorylation during colitis, confirming the potential pathogenic role of cGAS–STING signaling pathway in colitis." (PMID 37566032, 2023). "To explore the effect of cGAS loss on the colon, we performed DSS-colitis experiments in cGAS germline knockout (KO) mice." (PMID 34158863, 2021). "Furthermore, DSS-induced colitis was significantly mitigated by intraperitoneal injection of RU.521, a selective cGAS inhibitor, which improved weight loss, disease activity index score, shortened colon length, and histopathological manifestations." (PMID 40621423, 2025). "cGAS deficiency reduced the expression level of autophagic proteins, which led to worsened colitis." (PMID 40621423, 2025). "Moreover, it was demonstrated that ablation of cGAS exacerbated colitis and CAC due to intestinal stem cell deficiency and impaired intestinal barrier integrity." (PMID 39113810, 2024). "Moreover, GSDMD deficiency aggravates experimental colitis through cyclic GMP-AMP synthase (cGAS)-dependent inflammation." (PMID 38248345, 2024). "Furthermore, a recent study demonstrated that the exacerbation of experimental colitis following the deficiency of pyroptosis executioner Gasdermin D (GSDMD) depends on the hyperactivation of cGAS-STING pathway." (PMID 37566032, 2023). "Importantly, inhibition of NF-κB, p-TBK1, and TBK1 at protein levels and transcription of Ifit-1, and Ifn-β were observed in the colon of cGAS deficient DSS-colitis mice." (PMID 34158863, 2021). "cGAS knockout mice were less susceptible to DSS-induced colitis." (PMID 34158863, 2021). "Overall, these data supported that cGAS may play a causal role in colitis." (PMID 34158863, 2021). "In conclusion, exogenous N8AS supplementation effectively ameliorates DSS-induced colitis, likely through suppression of the cGAS–STING pathway." (PMID 41257293, 2025). "For example, substance P was shown to alleviate DSS-induced colitis by suppressing cGAS-STING activation and downstream ferroptosis in colonic tissue." (PMID 41257293, 2025). "The findings showed that both LP and N8AS markedly suppressed the expression of cGAS–STING pathway-associated proteins in RAW264.7 cells under both LPS stimulation and colitis microbiota supernatant exposure." (PMID 41257293, 2025).
colitis (continued). "C9orf72 overexpression attenuated DSS‐induced colitis and intestinal epithelial barrier damage by inhibiting the cGAS‐STING pathway." (PMID 39873292, 2025). "C9orf72 overexpression attenuated dextran sulfate sodium‐induced colitis and the intestinal epithelial barrier damage by inhibiting the cGAS‐STING pathway." (PMID 39873292, 2025). "Atrial natriuretic peptide was able to attenuate colitis in mice by inhibiting the cGAS-STING pathway." (PMID 38892524, 2024). "In additional research, inhibition of the cGAS–STING signaling pathway by atrial natriuretic peptide (ANP) was observed to alleviate DSS‐induced colitis." (PMID 38525112, 2024). "Other studies, however, have demonstrated a reduction in colitis severity with cGAS-STING activation." (PMID 39050748, 2024). "Our findings suggested that damaged mtDNA accrued in the cytosol and was released into the extracellular space, where it is sensed by cGAS in intestinal epithelial cells, boosting inflammation in colitis." (PMID 38725846, 2024). "To elucidate the downstream effectors of cGAS-STING signaling in colitis, we focused on the impact of cGAS-STING signaling on the ferroptosis pathway in colitis." (PMID 38725846, 2024). "Opposing evidence reported that GSDMD plays protective roles in IBD, since genetic ablation of GSDMD aggravated colitis by boosting cyclic GMP-AMP synthase (cGAS)-dependent inflammation." (PMID 37891577, 2023). "Accordingly, the administration of cGAS inhibitor RU.521 reduced weight loss, colon shortening, DAI score and histopathological findings in wild type murine models of DSS-induced colitis, totally rescuing the colitogenic phenotype in GSDMD-deficient mice." (PMID 37566032, 2023). "GSDMD deficiency-induced inflammation in macrophages that aggravated experimental colitis by boosting cyclic GMP-AMP synthase (cGAS)-dependent inflammation." (PMID 35677444, 2022). "GCV treatment significantly inhibited the upregulation of cGAS-STING pathway in DSS-induced colitis mice." (PMID 36467059, 2022). "Subsequently, we investigated the effects of GCV on the up-regulated expression of cGAS-STING pathways in DSS-induced colitis in mice." (PMID 36467059, 2022). "We finally investigated the effects of GCV on the expression levels of cGAS-STING pathways induced by DSS-colitis in STINGgt/gt mice." (PMID 36467059, 2022). "The cGAS protein levels were increased after treatment with DMXAA in the colonic tissue of mice with DSS-induced colitis." (PMID 35280696, 2022). "Taken together, our results demonstrated that cGAS plays an essential role in promoting the inflammatory response in colitis." (PMID 34158863, 2021). "In summary, these observations indicate that cGAS has a functional role in shaping the bacterial gut microbiota and is required to adjust microbiota expansion in colitis, which would be a niche of host-microbiome based potential therapeutic strategy." (PMID 34158863, 2021). "Our results demonstrated that cGAS was significantly up-regulated in inflamed human samples with CD and UC, and also in two independent experimental models, DSS-colitis and antibiotic-associated diarrhea." (PMID 34158863, 2021). "In summary, LP can alleviate colitis by regulating Gut microbiota/N8AS/cGAS-STING on one hand." (PMID 41257293, 2025). "However, in colitis, GSDMD in colonic macrophages mitigates epithelial damage caused by invasive intestinal pathogens via the cGAS signaling pathway, highlighting its protective role in immune defense." (PMID 39994107, 2025). "Brefeldin A, a fungal metabolite identified as an inhibitor of protein trafficking, may ameliorate colitis by suppressing the activation of cGAS-STING pathway and NLRP inflammasome." (PMID 40621423, 2025). "Additionally, macrophage-specific deletion of GSDMD exacerbates colitis by enhancing cyclic GMP-AMP synthase-mediated inflammatory responses." (PMID 40041420, 2025).
colitis (continued). "Thus, we confirmed that SP depended on its receptor NK1R to attenuate inflammation and ferroptosis through the cGAS-STING pathway in colitis." (PMID 38725846, 2024). "In conclusion, we found that cGAS-STING pathway-related genes may play different roles in colitis and tumors." (PMID 38831059, 2024). "Additionally, our previous study found that GSDMD in intestinal macrophages controlled colitis by regulating cGAS-mediated inflammatory responses." (PMID 38807373, 2024). "Moreover, the survival of wild‐type mice was significantly improved after treatment of DSS‐induced colitis with the cGAS inhibitor RU." (PMID 38525112, 2024). "The discrepancies seen between studies showing the canonical cGAS-STING pathway to induce or suppress the formation of colitis could be due to utilization of different colitis inducing models or differences in microbiota." (PMID 39050748, 2024). "In summary, SP not only inhibits cGAS-STING via preventing mtDNA leakage into the cytoplasm but also directly suppresses the STING pathway, eventually mitigating inflammation and ferroptosis to alleviate intestinal epithelium damage caused by colitis." (PMID 38725846, 2024). "Interestingly, we found that the expression of the cGAS-STING pathway actually decreased during the process of colitis-carcinoma transformation." (PMID 38831059, 2024). "Inhibition of the cGAS-STING-dependent signaling pathway attenuates chemically induced colitis." (PMID 39050748, 2024). "Inhibition of the cGAS-STING-dependent signaling pathway with atrial natriuretic peptide (ANP) or the herbal supplement Si-Ni-San has also been shown to attenuate chemically-induced colitis in mice." (PMID 39050748, 2024). "A recent paper further links cGAS and inflammsome signalling to colitis." (PMID 35712726, 2022). "Moreover, cGAS-STING pathways were upregulated in DSS-colitis mice and in UC patients and the severity of DSS-colitis and dysbiosis were attenuated in STING deficient mice." (PMID 36467059, 2022). "In the present study, we tested a hypothesis that GCV may have therapeutic effects on DSS-induced colitis in mice, possible through acting on cGAS-STING signaling." (PMID 36467059, 2022). "On the 9th-day post DSS challenge, where the severity of colitis nearly reached its peak, we observed a dramatic up-regulation of cGAS and downstream effectors at protein and mRNA levels in the inflamed colon following DSS treatment compared to the drinking water groups as controls." (PMID 34158863, 2021). "cGAS-deficient mice showed modest inflammatory response and polyp formation by DSS treatment, and cGAS inhibitor remarkably alleviated the clinical signs of colitis in mice." (PMID 33485379, 2021). "In addition to enhancing pyroptosis, GSDMD in colonic macrophages regulates cGAS-mediated inflammatory responses, which protect against intestinal bacterial invasion and epithelial damage following mucosal barrier disruption, thus mitigating colitis." (PMID 39994107, 2025). "Collectively, this study utilizing mice with fibroblast-specific OTUD3 deficiency or with UC-associated Otud3 SNP knock-in provided evidence that cGAS-STING-mediated type I IFN responses exacerbate the development of DSS-induced colitis in the absence of OTUD3 or presence of UC-associated Otud3 SNP." (PMID 41155222, 2025). "However, it remains unclear whether the intestinal cGAS-STING pathway is involved in IEC ferroptosis during colitis and how SP/NK1R signaling affects it in maintaining epithelial homeostasis." (PMID 38725846, 2024). "Studies have shown that activation of the cGAS–STING signaling axis represents a key pathway that exacerbates inflammatory responses and promotes the progression of colitis." (PMID 41257293, 2025). "In DSS-induced colitis models, IGF2 levels were reduced, but recombinant IGF2 restored IGF2R expression, blocked cGAS-STING signaling, preserved tight junction proteins (ZO-1, occludin), and promoted epithelial regeneration." (PMID 40507791, 2025).